MTOR (mechanistic target of rapamycin kinase)
Diseases named in the same sentence as MTOR in open-access papers (continued):
Sharing a sentence is not in itself a finding about the gene and the disease.
depression (continued). "Activation of the mechanistic target of rapamycin (mTOR), as well as increased levels of BDNF, may increase long-term potentiation and result in an improvement in the symptoms of depression." (PMID 30034974, 2018). "Furthermore, other down-stream signaling molecules, such as mTOR, P70S6K, and eIF4B, have been shown to be increased in major depressive disorder." (PMID 29163244, 2017). "Additionally, evidence has also supported the link between RA and depression through the activation of intracellular signaling pathway, such as SAPK/MAPK and PI-3K/AKT/mTOR." (PMID 26857028, 2016). "Previous studies have shown that these effects are linked to synaptic mechanisms in the medial prefrontal cortex involving the mTOR pathway, although how these biological changes relate to the emotional symptoms of depression has not been elucidated." (PMID 25740288, 2015). "The study revealed that NAc-DBS could attenuate depression-like behaviors, restore high gamma oscillation power and enhance synaptic spine density, potentially by increasing BDNF protein expression level and activating AKT/mTOR signaling pathway." (PMID 41234534, 2025). "However, in another dexamethasone-induced depression model, rosiglitazone exerts antidepressant effects via NGF activation and decreases the levels of phosphorylated AKT and mechanistic target of rapamycin kinase (mTOR), which conflicts with the conclusions above." (PMID 40783715, 2025). "This rapidly induced neuroplasticity is mediated via the stimulation of TrkB, mTOR, and intracellular 5-HT2A signaling pathways and is thought to be essential to the therapeutic effects of ibogaine and other psychoplastogens on complex mental health conditions, such as depression and SUD." (PMID 37675046, 2023). "Furthermore, a plethora of studies showed that the PTEN/AKT/mTOR or BDNF/synaptophysin pathway was not changed in a variety of depression models compared to that of the control group." (PMID 36969556, 2023). "Eight proteins (p-AKT, p-ERK12, GluA1, p-MEK1, p-MEK2, p-P38, Syn1 and TrkB) in the AKT and MAPK signaling pathways were significantly altered in at least one depression model, while three proteins (p-mTOR, p-P70S6K, PSD95) in the mTOR signaling pathway were not altered." (PMID 37308476, 2023). "Thus, SSD may alleviate depression-like behaviors in CUMS-exposed rats by regulating the Homer1-mGluR5 and mTOR signaling pathways." (PMID 35610650, 2022). "Therefore, the restoration of BDNF/PI3K/Akt/mTOR expression by CYDXF may be attributed to, at least in part, the effects of regulating endocrine disorders and/or treating the depressive disorders of these bioactive compounds." (PMID 32265693, 2020). "Activated mTOR and lessened activity of AMPK were also revealed in the hippocampus and PFC of the CUMS-induced animal model, which suggests that different animal models of depression (surgery or stress) may share a common nutrient compensatory mode." (PMID 31480539, 2019). "We currently do not know whether modulating the mTOR pathway in the brain is sufficient to reverse chronic pain-related symptoms including hypersensitivity or comorbidities including anxiety and depression." (PMID 31194026, 2018). "The direct role of mTOR signaling in the antidepressant-like effects of sarcosine on rats in the FST model was further examined using pretreatment with rapamycin, which resulted in a complete blockade of the antidepressant-like effects of sarcosine in the FST depression model." (PMID 26150775, 2015). "The involvement of the mTOR-regulated VTA-mPFC (Ventral tegmental area-medial prefrontal cortex) neural loop on PD-related depression in the MPTP-induced mouse model has been reported, which for the first time verified the neural loop hypothesis in PD-related depression using PD animal model." (PMID 35645772, 2022).
depression (continued). "Interestingly, one study in Wistar-Kyoto rats, a putative animal model of depression, found that chronic administration of ketamine for 11 days at very low doses (0.25 or 0.5 mg/kg) did elevate phosphorylated mTOR in the hippocampus, yet did not affect autophagy markers." (PMID 31396078, 2019). "Thus, mTOR and BDNF pathway may be a link between zinc, depression and neural plasticity." (PMID 28299207, 2017). "However, it is not known if mTOR phosphorylation is involved, via chronic fluoxetine administration, in the reversal of the depression-like behaviors, nor is it understood whether mTOR phosphorylation is necessary for synaptic protein expression." (PMID 26522512, 2015). "Preclinical studies accounted for a significant reduction in mTOR/p70S6K signaling in the PFC of patients experiencing depression, where, ketamine (noncompetitive NMDA receptor antagonist) imply rapid anti-depressant effect by modulating mTOR activation." (PMID 32860199, 2020). "Additionally, in another animal model of depression, namely, social defeat stress (SDS), mTOR does not play a role in the antidepressant effect of (R)-ketamine, in contrast to (S)-ketamine, the action of which is dependent on the activation of this kinase." (PMID 40342162, 2025). "However, the interaction mechanisms of AMPK with other signaling pathways, such as the mammalian target of rapamycin (mTOR) and PI3K/Akt, and their roles in regulating mitochondrial energy metabolism and depression have not been fully elucidated." (PMID 40699781, 2025). "Yangxin Dingji capsule has a good effect on PD patients with depression, which can alleviate the development of the disease, improve non-motor symptoms, and reduce depression, which may play a role by affecting the PI3K/AKT/mTOR signaling pathway." (PMID 37505150, 2023).
Alzheimer disease (220 papers, 2010 to 2026). A progressive, neurodegenerative disease characterized by loss of function and death of nerve cells in several areas of the brain leading to loss of cognitive function such as memory and language. "We have shown that almost half of the genes predisposing to autism and two-fifths of the genes predisposing to Alzheimer’s disease are directly related to the mTOR signaling pathway." (PMID 41155356, 2025). "Our analysis has shown that the sets of genes predisposing to ASD (from the SFARI database) and to Alzheimer’s disease have 148 common genes, out of which 75 are directly related to mTOR signaling pathway." (PMID 41155356, 2025). "Rapamycin also inhibited hippocampal long-term depression in mice involving activation of p-mTOR and inhibiting the cognitive deficits associated with mTOR activation in a mouse model of Alzheimer’s disease." (PMID 39946495, 2025). "Protein kinase-B (Akt) and the mechanistic target of rapamycin (mTOR) signaling pathways are implicated in Alzheimer’s disease (AD) pathology." (PMID 38182004, 2024). "In line with this, reduced mTOR activity restricted to the synapse has been found to be associated with impairment of activity dependent protein synthesis in Alzheimer's disease mice." (PMID 39192595, 2024). "Overproduction of reactive oxygen species (ROS) alternates the mammalian target of rapamycin (mTOR) pathway, which is associated with the development of Alzheimer’s disease." (PMID 37687032, 2023). "Of note, recent studies highlighted the importance of a precise pharmacological regulation of mTOR activity in NSCs, since hyperactive mTOR is associated with Alzheimer's Disease both in patients and mouse models." (PMID 36636818, 2023). "Lnc_Atg13 was an important component of the mTOR pathway, which contributes to the synthesis of synaptic proteins and is strongly linked to the pathophysiology of Alzheimer’s disease." (PMID 37106826, 2023). "Uncontrolled mTOR up-regulation has been linked to the complex molecular chain that underlies Alzheimer’s disease (AD)." (PMID 38002034, 2023). "Upregulation of the mTOR signaling system is linked to major pathogenic processes in Alzheimer's disease." (PMID 37255721, 2023). "In fact, oxidative stress and altered protein metabolism leading to insoluble aggregates and membrane unsaturation are processes under the control of mTOR that have been associated with the development of Alzheimer’s disease (AD)." (PMID 35955882, 2022). "Imbalances in the mTOR signaling pathway are strongly associated with NDDs, such as Alzheimer’s disease and PD." (PMID 35457010, 2022). "Previous studies also indicate a connection between mTOR hyperactivity and formation of abnormally hyperphosphorylated Tau protein, which is associated with neurodegenerative diseases such as Alzheimer’s disease." (PMID 35276811, 2022). "In fact, Tau protein has been implicated as the PI3K/AKT/mTOR pathway downstream effector to control neurite outgrowth, and its hyperphosphorylation is considered to be the basis of neuronal degeneration in Alzheimer’s disease." (PMID 36248658, 2022). "The mammalian target of rapamycin (mTOR) plays a critical role in controlling cellular homeostasis, and its dysregulation has been implicated in Alzheimer’s disease (AD)." (PMID 35965317, 2022). "Unrestrained mTOR up-regulation has also been linked to tau and amyloid β hyperphosphorylation and aggregation in Alzheimer’s disease." (PMID 34885795, 2021). "mTOR inhibitors are currently the only pharmacological treatment shown to extend lifespan in model organisms, and mTOR signaling has been directly implicated in age-associated disorders such as Alzheimer’s disease." (PMID 33922083, 2021). "Many neuropsychiatric diseases and neurodevelopmental disorders, such as Alzheimer’s disease and autism, are also associated with mTOR." (PMID 35096558, 2021).
Alzheimer disease (continued). "Upregulation of the mammalian target of rapamycin (mTOR) pathway has also been implicated as a major pathological process leading to Alzheimer’s disease." (PMID 30705766, 2019). "Increased mTOR activity is associated with development of Alzheimer’s disease (AD) in vitro and in vivo models, and with Huntington disease in animals and humans." (PMID 30067827, 2018). "mTOR is a serine/threonine protein kinase and its hyperactivity is involved in the pathophysiology of Alzheimer's disease (AD) and associated cognitive deficits." (PMID 30564080, 2018). "Such an analysis may reveal similarities and differences in the evolution of both ASD and Alzheimer’s disease predisposition genes, as well as the genes of the mTOR signaling pathway." (PMID 41155356, 2025). "The contrasting outcomes regarding the effect on p-mTOR may be attributed to the different models employed to induce Alzheimer’s disease, which caused suppression of p-mTOR." (PMID 40325262, 2025). "Moreover, there is evidence from a bidirectional Mendelian randomization study that points to Alzheimer's disease being associated with decreased BCAAs levels 81, while leucine has been demonstrated to promote AD via a mTOR-dependent mechanism." (PMID 39512690, 2024). "Additionally, the “Endo-Lysosomal Dysfunction” concept of Alzheimer’s disease is supported by the disruption of lysosomal protein breakdown pathways caused by persistent mTOR activation." (PMID 38002034, 2023). "Further research found that mice with associated genes knockout in Alzheimer's disease showed decreased mTOR pathway activity, impaired glycolysis function and increased neuronal autophagy, especially the triggering receptor expressed on myeloid cells‐2 (TREM‐2) gene." (PMID 37132040, 2023). "Most interestingly, Caccamo and colleagues found an association between Alzheimer’s disease, such as cognitive impairment and mTOR hyperactivity, in a mouse model and additionally showed that genetic mTOR suppression leads to reduction of beta-amyloid plaques and cognitive deficiencies." (PMID 35276811, 2022). "However, in Alzheimer’s disease (AD), mTOR alternately plays important pathogenic roles by inhibiting both insulin signaling and autophagic removal of β-amyloid (Aβ) and phospho-tau (ptau) aggregates." (PMID 34215308, 2021). "It has also been implicated in Alzheimer’s disease (AD) with neuronal cells and hippocampal slices of AD transgenic mice experiencing dysregulated mTOR and synaptic plasticity in response to treatment with the toxic amyloid β (Aβ1–42) peptide, which has been implicated in AD." (PMID 25119265, 2014). "It is also noteworthy that similar white matter abnormalities have been linked to Alzheimer’s disease, suggesting that mTOR/mTORC targeted therapeutic interventions may benefit other neurodegenerative diseases in which white matter degeneration is a dominant feature." (PMID 40149949, 2025). "mTOR has been implicated in a number of processes critical for proper brain function, including regulating neural development, circuit formation, and autophagy (which is thought to protect the brain from neurodegenerative disorders such Parkinson’s and Alzheimer’s diseases)." (PMID 39107687, 2024). "The neurodegenerative process in Alzheimer’s disease (AD) is characterized by synaptic damage leading to progressively impaired synaptic plasticity and eventual neuronal loss driven by multiple signaling abnormalities, including the overactivation of mammalian target of rapamycin (mTOR)." (PMID 37457922, 2023). "For instance, STAT2 regulates Sirt4 transcription and activates the mTOR pathway, thereby promoting neuronal apoptosis in Alzheimer’s disease." (PMID 41523985, 2026). "In contrast, circRNA NF1-419 increased autophagy in astrocytes via PI3K-I/Akt-AMPK-mTOR and PI3K-I/Akt–mTOR signaling pathways and affected inflammatory mediators and delayed the development of dementia in an animal model of Alzheimer’s disease." (PMID 41245147, 2025).
Alzheimer disease (continued). "In this study, we explored the therapeutic potential of PF-04691502, a dual PI3K/mTOR inhibitor, in Alzheimer’s disease (AD)-like pathology using male and female B6.Cg-Tg(APPswe, PSEN1dE9)85Dbo/Mmjax mice (APP/PS1), a well-established transgenic model of AD." (PMID 41002439, 2025). "Data appear inconsistent concerning the impact of various Alzheimer’s disease models on the PI3K/AKT/mTOR pathway or its individual components." (PMID 40325262, 2025). "The prevention of neuronal cellular senescence in age-related disorders including Alzheimer’s disease, can also be correlated with the induction of autophagy by inhibiting the mTOR pathway." (PMID 41346437, 2025). "To address this gap, we have reconstructed and analyzed the gene networks linking autism spectrum disorders, Alzheimer’s disease, and mTOR signaling." (PMID 41155356, 2025). "Studies have reported that mTOR regulates protein synthesis and degradation in the context of Alzheimer’s disease (AD) pathogenesis." (PMID 40843259, 2025). "Impairment of the PI3K/AKT pathway during Alzheimer’s disease progression, coupled with successive mTOR stimulation, has been shown to enhance tau phosphorylation, amyloid-beta deposition, and the cessation of autophagy, thereby exacerbating neurodegeneration." (PMID 40325262, 2025). "Disrupted mTOR signaling appears in conditions like Parkinson’s and Alzheimer’s diseases, where excessive mTOR activity reduces autophagy and promotes protein accumulation." (PMID 40799366, 2025). "Rapamycin, an mTOR inhibitor used clinically for immunosuppression, shows promise for repurposing in age-related disorders, including Alzheimer's disease (AD)." (PMID 41046300, 2025). "To assess the genetic and pathogenic similarity between ASD and AD, we have reconstructed and analyzed the gene networks linking autism spectrum disorders, Alzheimer’s disease, autoimmunity, and the mTOR signaling pathway." (PMID 41155356, 2025). "Lastly, mTOR, a conserved serine/threonine protein kinase, is dysregulated in Alzheimer’s disease through Aβ-induced autophagy impairment, endoplasmic reticulum stress, cell apoptosis, and mitochondrial dysfunction." (PMID 38195609, 2024). "Five pathways were in common to all the NVU cell types, including Alzheimer’s disease, glutamatergic synapse, mTOR, MAPK, and Wnt signaling." (PMID 39456952, 2024). "The depletion of any of these enzymes elevates Hcy-thiolactone and N-Hcy-protein, which dysregulate the Phf8 → H4K20me1 → mTOR → autophagy pathway and upregulate APP, causing Aβ accumulation, a hallmark of Alzheimer’s disease." (PMID 39125665, 2024). "In Alzheimer’s disease, hsa-miR-100–5p is known to regulate neuron survival by targeting the Mammalian Target of Rapamycin (mTOR) pathway, a central player in regulating many fundamental cell processes and a critical factor in tumor metabolism." (PMID 38343804, 2024). "If successful, the study would provide a strong rationale for large-scale evaluation of mTOR-inhibitors as a potential disease-modifying treatment in Alzheimer’s disease." (PMID 38575854, 2024). "Emerging pre-clinical evidence from the last decade displayed the surprising effectiveness of mTOR inhibitors in ameliorating Alzheimer's Disease (AD), a common neurodegenerative disorder characterized by progressive cognitive function decline and memory loss." (PMID 38873415, 2024). "A large body of evidence, replicated in many mouse models of Alzheimer’s disease (AD), supports the therapeutic efficacy of the oral mammalian target of rapamycin inhibitors (mTOR-Is)." (PMID 38139306, 2023). "On the other hand, inhibition of mTOR attenuated cognitive deficits and reduced amyloid-beta levels in a mouse model of Alzheimer’s disease." (PMID 37528226, 2023). "The activation of apoptosis by inducing the expression of SIRT6 and inhibiting the mTOR pathway by 3‐iodothyronamine was found in a transgenic model of Alzheimer's disease." (PMID 37381696, 2023).